PLA2G7 (phospholipase A2 group VII)
Diseases named in the same sentence as PLA2G7 in open-access papers (continued):
Sharing a sentence is not in itself a finding about the gene and the disease.
prostate carcinoma (14 papers, 2011 to 2025). A carcinoma that arises from epithelial cells of the prostate gland. "The results indicated that PLA2G7 is a cancer-selective biomarker in 50% of prostate cancers and associates with aggressive disease." (PMID 22202492, 2011). "The results confirmed that PLA2G7 expression strongly associates with prostate cancer." (PMID 22202492, 2011). "PLA2G7 has also been reported as a novel prognostic factor in prostate cancer and a potential therapeutic target through apoptosis regulation." (PMID 40169540, 2025). "In prostate cancer, the genes PLA2G7, HPGD, EPHX2, and CYP4F8 exhibit significantly altered expression." (PMID 38172792, 2024). "The IPA demonstrated that important biochemical molecules such as VEGF, ERK1/2, p38 MAPK and PLA2G7, NADPH oxidase, SMAD3 and ODC1 were involved in the biological network associated with berberine against prostate cancer." (PMID 29029409, 2017). "We found one amplified gene in the in-frame fusion samples, hydroxyprostaglandin dehydrogenase 15-(NAD) (HPGD), which was reported as a therapeutic target in prostate cancer due to its involvement in the arachidonic acid pathway with PLA2G7, EPHX2, and CYP4F8." (PMID 29299133, 2017). "In this study, we elucidated the potential of PLA2G7 as a biomarker and therapeutic drug target in prostate cancer management." (PMID 22202492, 2011). "In order to reveal the changes induced by PLA2G7 impairment in prostate cancer cells, lipidomic and gene expression profiling was performed in cultured prostate cancer cells." (PMID 22202492, 2011). "Since statins are known to inhibit PLA2G7 in atherosclerotic plaques, their ability to reduce PLA2G7 expression and activity in VCaP prostate cancer cells was elucidated." (PMID 22202492, 2011). "By determining the expression level of PLA2G7 in malignant and healthy prostate samples from 453 prostate cancer patients, the biomarker potential of PLA2G7 and the size of the potential patient group benefiting from PLA2G7 inhibition therapy, was evaluated." (PMID 22202492, 2011). "This knowledge in combination with frequent expression and vital function of PLA2G7 in ERG positive prostate cancer cells provides a significant opportunity for drug repositioning." (PMID 22202492, 2011). "Since VCaP cells do not migrate in wound healing experiment nor grow in 3D matrix, PC-3 cells, expressing PLA2G7, were selected as a model to validate the functional effect of PLA2G7 silencing on prostate cancer cell motility and invasion." (PMID 22202492, 2011). "Here we show for the first time that statins reduce the enzymatic activity of PLA2G7 in prostate cancer cells." (PMID 22202492, 2011). "The alterations induced by PLA2G7 silencing highlighted the potential of PLA2G7 inhibition as an anti-proliferative, pro-apoptotic and anti-migratorial therapeutic approach in prostate cancer." (PMID 22202492, 2011). "Taken together, our results support the potential of PLA2G7 as a biomarker and a drug target in prostate cancer and present a rationale for combining PLA2G7 inhibition with the use of statins in prostate cancer management." (PMID 22202492, 2011). "In order to reveal the molecular alterations induced by PLA2G7 impairment, lipidomic and gene expression profiling was performed in response to PLA2G7 silencing in cultured prostate cancer cells." (PMID 22202492, 2011). "Immunohistochemical staining results indicated that PLA2G7 is a potential prostate cancer biomarker present in approximately 50 percent of tumors in our cohort, and associating with high grade prostate tumors." (PMID 22202492, 2011). "PLA2G7 promotes several oncogenic processes such as cell viability, migration and invasion in prostate cancer." (PMID 22202492, 2011). "STAT3 is also known to promote androgen-independent growth in cultured prostate cancer cells, giving additional support to the beneficial effect of PLA2G7 inhibition in prostate cancer management." (PMID 22202492, 2011).
prostate carcinoma (continued). "In order to reveal the lipidomic changes induced by PLA2G7 impairment, cellular lipidomic profiles were analyzed in ERG positive VCaP prostate cancer cells expressing PLA2G7 at high levels." (PMID 22202492, 2011). "In conclusion, we propose PLA2G7 as a prognostic and theranostic biomarker, as well as a putative therapeutic target in prostate cancer." (PMID 22202492, 2011). "PLA2G7 impairment modulated the levels of multiple lipids in prostate cancer cells, the most striking being the reduction in lysophosphatidylcholine (LPC)." (PMID 22202492, 2011). "The cellular responses to PLA2G7 inhibition were studied to understand the PLA2G7 driven biological and oncogenic processes in prostate cancer cells." (PMID 22202492, 2011). "We have recently identified phospholipase 2 group VII (PLA2G7) as a potential drug target especially in ERG oncogene positive prostate cancers." (PMID 22202492, 2011). "The antineoplastic effect of statins combined with PLA2G7 impairment was studied in prostate cancer cells to evaluate the potential for repositioning of in vivo compatible drugs developed for other indications towards anti-cancer purposes." (PMID 22202492, 2011). "PLA2G7 promoted cell migration and invasion in prostate cancer." (PMID 37704909, 2023). "Furthermore, a synergistic anti-proliferative effect was observed in response to combinatorial treatment with PLA2G7 inhibition and statins in cultured prostate cancer cells." (PMID 22202492, 2011). "In addition to accelerated adhesion to fibronectin, PLA2G7 silencing reduced cell migration and invasion in prostate cancer cell culture models." (PMID 22202492, 2011). "However, the molecular alterations in response to PLA2G7 expression in prostate cancer remain to be elucidated." (PMID 22202492, 2011). "Moreover, this is the first study connecting statin treatment with reduced PLA2G7 activity in prostate cancer cells, and presents a rationale for combining PLA2G7 inhibition with statins in prostate cancer management." (PMID 22202492, 2011). "However, the migratory capacity of PC-3 cells both in 2D and 3D cultures was decreased confirming the role of PLA2G7 in promoting prostate cancer cell migration and invasion." (PMID 22202492, 2011). "Moreover, the antineoplastic effect of statins combined with PLA2G7 impairment was studied in prostate cancer cells to evaluate the potential of repositioning of in vivo compatible drugs developed for other indications towards anti-cancer purposes." (PMID 22202492, 2011). "Moreover, the anti-proliferative effect of PLA2G7 silencing was potentiated by lipid-lowering statins in prostate cancer cells." (PMID 22202492, 2011). "Interestingly, PLA2G7 silencing reduced the expression of aldehyde dehydrogenase 1A1 (ALDH1A1), described as a prostate cancer stem cell marker and associated with poor prostate cancer outcome." (PMID 22202492, 2011). "The aim of this study is to validate PLA2G7 as potential cancer selective biomarker, deepen our understanding on its molecular and cellular function and study the growth inhibitory potential of PLA2G7 impairment combined with statin exposure in cultured prostate cancer cells." (PMID 22202492, 2011). "Furthermore, PLA2G7 silencing was shown to sensitize prostate cancer cells to oxidative stress." (PMID 22202492, 2011). "Furthermore, as combinatorial therapeutic approaches may be required to obtain significant therapeutic progress, the ability of statins to potentiate the anti-proliferative effect of PLA2G7 impairment in prostate cancer cells was investigated." (PMID 22202492, 2011).
prostate carcinoma (continued). "Silencing of three genes (DLX1, PLA2G7 and RHOU) in the prostate cancer cell lines PC3 and VCaP by siRNA resulted in marked growth arrest and cytotoxicity, particularly in 3D organotypic cell culture conditions." (PMID 27196083, 2016). "Six target genes were subjected to protein validation: GPR116, NPY and PLA2G7, three genes over-expressed in ERG+ tissues, and AZGP1, HPGD and TFF3, three genes down-regulated in ERG+ prostate cancer tissues." (PMID 23390522, 2013). "The antiproliferative and pro-apoptotic effect of PLA2G7 impairment was seen in the ERG positive prostate cancer cells, indicating that ERG positive prostate cancer cells are dependent on PLA2G7 function." (PMID 22202492, 2011). "Moreover, PLA2G7 impairment reduced aldehyde dehydrogenase activity, considered as a marker of prostate cancer stem cells as well as tumor- and metastasis-initiating prostate cancer cells supporting the possibility that PLA2G7 expression may have prognostic significance." (PMID 22202492, 2011). "Since PLA2G7 is induced by ERG and is highly expressed especially in the ERG positive prostate cancers, it is a putative biomarker for this subgroup of prostate cancers." (PMID 22202492, 2011). "The ezetimibe targeted phospholipase A2 group VII (PLA2G7) has also been found to have tight correlation with cancer cachexia and put forward as therapeutic target for prostate cancer, supporting the possibility of ezetimibe used in clinical therapy in advanced cancer stages." (PMID 36843944, 2023). "In prostate cancer, PLA2G7 is highly enriched in primary tumor samples, but not in the adjacent normal tissues, and is positively associated with poor survival and more aggressive disease." (PMID 27487154, 2016). "The anti-migratory effect was not restricted to ERG positive prostate cancer cells supporting the rationale of PLA2G7 inhibition in the prevention and treatment of aggressive and metastatic tumors." (PMID 22202492, 2011). "Here, the expression profile of PLA2G7 was studied in 1137 prostate cancer and 409 adjacent non-malignant prostate tissues using immunohistochemistry to validate its biomarker potential and putative association with disease progression." (PMID 22202492, 2011). "PLA2G7 expression was studied in a large set of non-malignant prostate and prostate cancer tissues using immunohistochemistry." (PMID 22202492, 2011). "Vainio et al196 observed that PLA2G7 overexpression was present in a majority of clinical prostate tumors and correlated positively (r = 0.66, P < .001) with the expression of ERG, an E twenty‐six gene (ETS)‐related gene that may be involved in the initiation and progression of prostate cancer." (PMID 31140638, 2020). "ERG was shown to induce the expression of PLA2G7, and knock-down of PLA2G7 significantly reduced the growth of ERG positive, but not ERG negative, prostate cancer cells in vitro, indicating potential as a biomarker and personalized drug target in ERG positive prostate cancers." (PMID 22202492, 2011).
asthma (13 papers, 2008 to 2025). "Analysis of the biomarker-disease network map revealed that ALOX5, HMOX1, and PLA2G7 were strongly associated with asthma." (PMID 41030501, 2025). "ALOX5, HMOX1, and PLA2G7 are genes that have been implicated in asthma." (PMID 41030501, 2025). "A large number of diseases that have been linked to the PLA2G7 gene polymorphism are of cardio-cerebral origin, but asthma, schizophrenia, chronic kidney disease, multiple sclerosis, ulcerative colitis and Kawasaki illness have also been linked to PLA2G7 polymorphisms." (PMID 35694871, 2022). "Variants in PLA2G7 have also be found to be associated with the risk of asthma." (PMID 18776951, 2008). "The distribution of asthma across PLA2G7 quartiles was different (22.19% vs. 14.13%; p = 0.001) and distribution of COPD across quartiles of PLA2G7 was similar (2.85% vs. 1.27%; p = 0.27)." (PMID 34800009, 2021). "However, despite the increasing interest in the role of these genes in asthma, there remains a lack of studies examining the relationship between PLA2G7 and asthma." (PMID 41030501, 2025).
cerebrovascular disease (13 papers, 2010 to 2026). "The PLA2G7 coding enzyme, Lp-PLA2, has attracted considerable attention due to its crucial function in platelet gathering in cardiovascular and cerebrovascular diseases." (PMID 25543670, 2015).
Sepsis (12 papers, 2012 to 2025). Sepsis is defined as life-threatening organ dysfunction caused by a dysregulated host response to infection. "The best performing signature for discriminating sepsis from SIRS was CMTM5/CETP/PLA2G7/MIA/MPP3 (AUC=0.9758)." (PMID 38332914, 2023). "The best performing panel to differentiate sepsis from SIRS was CMTM5/CETP/PLA2G7/MIA/MPP3 using our dataset (AUC=0.9758)." (PMID 38332914, 2023). "SIRS-specific biomarkers MPP3, PLA2G7, GPR124 and ARHGEF10L correlated positively with each other and negatively with the sepsis-specific biomarkers and CRP." (PMID 38332914, 2023). "SeptiCyte® RAPID is a gene expression assay measuring the relative expression levels of host response genes PLA2G7 and PLAC8, indicative of a dysregulated immune response during sepsis." (PMID 36851633, 2023). "For instance, the first host response gene expression assay for diagnosis of sepsis, SeptiCyte LAB, is based on the four marker genes CEACAM4, LAMP1, PLAC8 and PLA2G7." (PMID 34555028, 2021). "Recently, many genes have also been identified for sepsis diagnosis and prognosis; for example, SeptiCyte Lab combined with CEACAM4, LAMP1, PLA2G7, and PLAC8 genes was identified to determine which patients had sepsis." (PMID 32922168, 2020). "SeptiCyte® RAPID (Seattle, WA, USA) also represents a novel diagnostic tool that assesses the host immune response by quantifying PLA2G7 and PLAC8 gene expression in whole blood, offering potential for early differentiation between sepsis and sterile inflammation." (PMID 41096721, 2025). "However, these markers correlated well with a prognosis/recovery in the sepsis groups, particularly ARHGEF10L and PLA2G7." (PMID 38332914, 2023).
breast carcinoma (9 papers, 2011 to 2025). "High PLA2G7 expression in tumours has been associated with aggressive types of prostate and breast cancers and with a poor survival rate of cancer patients." (PMID 34427055, 2021). "Past studies have confirmed that aberrant activation of the Wnt/β-catenin signaling is associated with tumorigenesis and metastasis in breast cancer, while the role of platelet-activating factor acetylhydrolase (PLA2G7/PAF-AH) in this signaling pathway remains unclear." (PMID 36614323, 2023). "In breast cancer, PLA2G7 has been identified as a regulator of the Wnt signaling pathway and hormone receptor negativity, as well as a factor involved in epithelial-mesenchymal transition." (PMID 40169540, 2025). "PLA2G7 plays a regulatory role in the Wnt signaling pathway in breast cancer." (PMID 40869314, 2025). "Interestingly, we found that breast cancer cell MCF and non-small lung cancer cell H1299 were also able to induce THP-1 cells to express PLA2G7." (PMID 27487154, 2016). "The Pla2g7 and Paics trends identified in this study are consistent with those reported for breast cancer in mice and in non-glioma types of cancer, respectively." (PMID 21649900, 2011). "Furthermore, we found that CRC cells HCT116 and SW480 who are constitutively express PLA2G7 do not induce THP-1 cells to expression this gene, whereas breast cancer cell MCF7 and non-small lung cancer cell H1299 who do not expression PLA2G7 themselves are able to induce this gene in THP-1 cells." (PMID 27487154, 2016).
ovarian carcinoma (5 papers, 2020 to 2023). A malignant neoplasm originating from the surface ovarian epithelium. "A changed distribution pattern of β-catenin within the cellular departments in BRCA mutant ovarian cancer cells caused by PLA2G7 gene knockdown confirmed this assumption." (PMID 34206491, 2021). "Phospholipase A2 group VII (PLA2G7) was expressed in BRCA1 mutant ovarian cancer as a protective factor and potential negative regulator of the Wnt signalling pathway." (PMID 37357306, 2023). "Silencing of its gene PLA2G7 caused activation of viability, proliferation, and migration of BRCA1 mutant ovarian cancer cells." (PMID 34206491, 2021). "By in vitro expression analysis, a relevant gene and protein expression of PLA2G7/PAF-AH was detected exclusively in the BRCA1-negative ovarian cancer cell line UWB1.289 (p < 0.05)." (PMID 34206491, 2021). "Patients and in vitro generated data indicate that PAF/PTAFR and PLA2G7/PAF-AH signaling plays a crucial role in BRCA1 mutant ovarian cancer." (PMID 34206491, 2021). "To assess the functional role of PLA2G7/PAF-AH and its possible impact on the Wnt/β-catenin signaling pathway in ovarian cancer, we performed in vitro experiments in the BRCA1-negative ovarian cancer cell line UWB1.289." (PMID 34206491, 2021). "Since the relevant gene and protein expression of PLA2G7/PAF-AH were detected exclusively in the BRCA1 mutant cell line UWB1.289, PAF-AH can be considered a new biomarker for BRCA1 mutant ovarian cancer, indicating good prognosis." (PMID 34206491, 2021). "The macrophage derived phospholipase PLA2G7 can produce extra-cellular LPA, which participate in the progress of ovarian carcinoma, and is related to the early recurrence of ovarian cancer." (PMID 32774171, 2020). "In this study, we evaluated a panel of 8 biomarkers, including B7-H3, IL-6, PLA2G7, Tie-2, GDF-15, IL-6 R alpha, sSDC1, and VCAM-1 selected based on their reported relevancy to ovarian cancer and multiplexing feasibility as a customized magnetic bead-based 8-plex immunoassay." (PMID 37357306, 2023). "Both PLA2G7 expression on mRNA level (p < 0.05) and PAF-AH expression on protein level (p < 0.05) were significantly increased in the BRCA1 mutant ovarian cancer cell line UWB1.289 compared to HOSEpiC and other ovarian cancer cell lines." (PMID 34206491, 2021).
colon tumor (4 papers, 2020 to 2025). "In colon tumorigenesis, high PLA2G7 expression has been proposed to play a causal role, and PLA2G7 deletion has been shown to decrease intestinal polyposis and colon tumor formation in ApcMin/+ mice." (PMID 40169540, 2025). "Of note, in human and murine colon cancer cell lines, silencing of the gene expressing Lp-PLA2 (PLA2G7) led to reduction of tumor size by 42% in vivo and the PLA2G7 knockout Apc Min/+ mice displayed vigorous suppression of intestinal polyposis and colon tumor formation." (PMID 34220834, 2021). "Three of the eight colonic tumor-related genes, ABCA1, PLA2G7, and SCARB1, were significantly correlated with GLS, the main enzyme for glutamate metabolism." (PMID 36843944, 2023).
colorectal cancer (4 papers, 2016 to 2025). A primary or metastatic malignant neoplasm that affects the colon or rectum. "We observed inducible, prolonged expression of PLA2G7, a secreted enzyme that is associated with pathogenesis of prostate and colorectal cancers, from THP-1 cells after co-culture with C666-1 cells or its conditioned medium." (PMID 27487154, 2016). "Studies on colorectal cancer have suggested that high PLA2G7 enzyme activity plays a key role in the development of the disease." (PMID 40869314, 2025). "Our anti-PLA2G7 mAbs inhibited PLA2G7 enzymatic activity and reduced PLA2G7-mediated cell migration in colorectal cancer cell lines." (PMID 40136470, 2025). "In a first cohort of patients with pancreatic and colorectal cancer, plasma PLA2G7 protein levels were significantly higher in patients who experienced weight loss within the past 3 months (i.e. weight‐losing) compared with healthy individuals." (PMID 34427055, 2021). "In colorectal cancer (CRC), increased activity and expression of PLA2G7 were detected in tumor tissues and plasma from CRC patients compared with samples from healthy donors." (PMID 27487154, 2016). "In addition, the function of PLA2G7 in cancers other than colorectal cancers has not been reported." (PMID 27487154, 2016).